IL6 (interleukin 6)
Diseases named in the same sentence as IL6 in open-access papers (continued):
Sharing a sentence is not in itself a finding about the gene and the disease.
breast cancer (continued). "IL-6 is often associated with the tumour microenvironment and clinically, circulating IL-6 level is associated with poor prognosis and low survival rate in patients with breast cancer, while IL-6 polymorphisms are linked to increased breast cancer risk." (PMID 35226704, 2022). "A number of studies have shown that elevated inflammatory markers in the serum of breast cancer patients, including IL-6, are associated with a poor prognosis of the disease." (PMID 36286034, 2022). "IL6 is highly expressed in basal breast cancer cell lines, which are also associated with elevated ORAI1." (PMID 35682546, 2022). "IL-6 has been also implicated in resistance to trastuzumab treatment for women with HER-2/Neu breast cancer subtype." (PMID 35163731, 2022). "The role of senescence-associated secretory phenotypes (SASPs) such as interleukin-6 (IL-6), IL-8, and matrix metalloproteases (MMPs), in breast cancer cell proliferation, invasion, and metastasis is worthy of exploration." (PMID 36291773, 2022). "IL-6 and IL-8 are cytokines associated with BCSCs and treatment resistance in breast cancer patients." (PMID 35847899, 2022). "Multiple mechanisms underlie breast cancer metastatic dissemination, including the interleukin-6 (IL-6)-mediated signaling pathway." (PMID 35371975, 2022). "Studies performed on breast cancer, and colorectal cancer identified a positive association of IL-6–174 G/C polymorphism with HCC development." (PMID 36215278, 2022). "Consistently, the drug‐activated autophagy was proven to reduce the secretion of IL‐6 in chondrocytes, while the suppression of autophagy by deleting Atg7 caused increased export of IL‐1β, IL‐6 and IL‐8 in adipocytes and breast cancer cells." (PMID 33963627, 2021). "IL-6 is an inflammatory cytokine where high serum levels of IL-6 have been shown to correlate with poor outcomes in breast cancer patients and several IL6 SNPs have been associated with breast cancer risk and prognosis." (PMID 34068181, 2021). "The secretomic profile that associated with cancer relapse and high grade breast cancer showed induced secretion of the proteins IL-6, CCL2 and PAI-1, all linked to cancer stem cell activation, metastasis and priming of the pre-metastatic niche." (PMID 34090457, 2021). "In this review, IL-6 signaling is implicated in chemoresistance and metastasis of various tumors, including breast cancer." (PMID 34359928, 2021). "In conclusion, this study reveals a novel function for EphA2 signaling in tumor cell–bone cell interactions involved in osteoclastogenesis and osteolysis associated with breast cancer metastasis, in part through regulation of cytokines such as IL‐6." (PMID 33869989, 2021). "Interleukin-6 (IL6) has also been implicated in mammary tumors from mice fed a HFD and in tumor cell lines derived from MMTV-K-Ras mice." (PMID 34371939, 2021). "For example, in breast cancer, MSCs secreting IL-6 causes protection of MCF-7 cells from cisplatin-induced apoptosis, which is mediated by activating STAT3 signaling pathway with the markedly decreasing expression of Bax." (PMID 34095111, 2021). "Previous studies indicated that a high serum level of IL-6 and its soluble receptor has an independent prognostic value, and is associated with the extent and tumor grade of breast cancer." (PMID 33517609, 2021). "IL-6 has been implicated as a driver in pre-clinical models of ER+ breast cancer, and high IL-6 serum and tumor levels have been associated with aggressiveness and poor outcome in patients." (PMID 33806019, 2021). "In a univariate logistic regression analysis, a high-risk IL-6 promoter genotype profile was significantly and strongly associated with increased risk of relapsed breast cancer (OR 7.19, 95% CI 1.47–35.30, p = 0.015)." (PMID 33483516, 2021). "IL-6 serum levels have also been shown to be significantly elevated in lung and breast cancer patients and associated with poor prognosis." (PMID 34124067, 2021).
breast cancer (continued). "High expression and increased serum level of harmful pro-inflammatory cytokines including resistin, TNF-α, IL-6, and IL-8 are associated with shorter survival and poor prognosis of breast cancer." (PMID 33517609, 2021). "Surprisingly, high-risk IL-6 promoter polymorphisms were strongly associated with HER2+ breast cancer relapse, which has potential therapeutic implications, as elevated intracellular IL-6 has been associated with trastuzumab resistance in pre-clinical models." (PMID 33483516, 2021). "For instance, it has been shown that high circulating levels of IL-1β and IL-6 are unfavorable prognostic indicators and directly associate with higher risk of recurrence and more aggressive type of disease in patients with breast cancer." (PMID 34344421, 2021). "Cross talk between nitric oxide-induced Notch causes the constitutive expression of IL-6 induced STAT3 is seen vital for breast cancer stemness paves the way to identify targets common to both pathways." (PMID 33964962, 2021). "A previous study on MDA-MB-231 and MCF-7 cell lines show that IL-6 and IL-10 are associated with good prognosis in breast cancer." (PMID 32560316, 2020). "IL-6 is present in a variety of cancers, such as colorectal and breast cancers, and is associated with a poor prognosis in cancer." (PMID 32309219, 2020). "A role for IL-11 signaling in breast cancer has been less well-described, but elevated levels of IL-11 and IL-11Rα are associated with poor patient outcomes and both IL-11 and IL-6 are associated with breast cancer metastasis into bone." (PMID 32765502, 2020). "The anti-invasive effect was related to the inhibition of with IL-6 linked signaling pathway, which has an important role in the progression, invasion, and metastasis of breast cancer." (PMID 32521759, 2020). "IL-6 is a pro-inflammatory cytokine that has been associated with both breast cancer risk and progression." (PMID 33004039, 2020). "In breast cancer, for example, cancer-associated adipocytes trigger radio-resistance by secreting IL-6." (PMID 32847008, 2020). "The treatment of RB-deficient breast cancer cells with an antibody that is capable of neutralizing IL-6 activity accelerated the accumulation of mitochondrial superoxide and subsequent cell death." (PMID 32244804, 2020). "This is the case of IL-6, for example, as high serum levels appear to be linked with higher rates of metastasis and shorter survival in breast cancer patients." (PMID 33597950, 2020). "IL6, secreted from adipocytes into circulation, has been shown to increase breast cancer risk and tumor size." (PMID 32824813, 2020). "The increased secretion of leptin promotes metastasis by increasing the expression of epithelial–mesenchymal transformation (EMT)- and metastasis-associated genes (SERPINE1, MMP-2, and IL-6) in breast cancer cells." (PMID 32674405, 2020). "TNFα, IL-6, and IL-1β are all elevated in obese breast cancer patients and are associated with breast cancer progression and outcomes." (PMID 32630445, 2020). "In fact, elevated serum levels of IL-6 have been associated with poor prognosis of lung and breast cancer." (PMID 31337349, 2019). "IL-6 induction is associated with a poorer prognosis in patients with breast cancer and serum IL-6 levels are increased with pathological grades." (PMID 30885232, 2019). "Collectively, these results demonstrate that the breast tumor expression levels of OSM and IL-6 are correlated and that elevated breast cancer tissue levels of these cytokines are associated with decreased survival." (PMID 31007849, 2019). "Given these contradictory results, more epidemiological studies with larger sample sizes should be conducted to explore the effect of IL-6 level on breast cancer risk." (PMID 30962499, 2019). "In fact, we have recently demonstrated that high tumor expression of OSM or IL-6 along with high VEGF expression is associated with poor survival in HER2- breast cancer patients." (PMID 31007849, 2019).
breast cancer (continued). "IL-6 has also been implicated in the malignant transformation of breast cancer stem cells and in the enhancement of cancer cell metastatic potential and epithelial to mesenchymal transition." (PMID 31491838, 2019). "Several studies implicated high levels of IL6 in poor prognosis and lesser treatment response in breast cancer." (PMID 30967156, 2019). "Elevated serum IL6 has been demonstrated to associate with clinical outcome in several cancers, including breast cancer and prostate cancer where IL6 has been shown to have pleiotropic properties." (PMID 31066211, 2019). "Increasing evidence suggests that high levels of serum IL-6 are associated with poor prognosis, advanced disease, and metastases in breast cancer patients." (PMID 31409371, 2019). "Previous studies have shown that high levels of inflammatory cytokines such as IL-6 increase the risk of breast cancer development and progression and that IL-6 also promotes cancer cell aggressiveness and metastasis to distant organs such as to the bone." (PMID 31007849, 2019). "OSM and IL-6 have previously been implicated in the production of proangiogenic factors such as VEGF to promote breast cancer progression and reduced patient survival." (PMID 31007849, 2019). "Interleukin-6 (IL-6) is commonly highly secreted in the breast cancer (BrCA) microenvironment and implicated in disease development." (PMID 31795965, 2019). "Serum IL-6 levels are high in the subjects with ductal carcinoma advanced stage and aberrantly elevated IL-6 is associated with a poor prognosis in breast cancer." (PMID 30631150, 2019). "Numerous reviews have also reported the strong association between interleukins and breast cancers, notably IL1β, IL6, and IL8." (PMID 31398937, 2019). "IL-6 levels also correlate to increased number of MDSCs, tumor-associated neutrophils (TANs), regulatory T cells (Tregs) in many cancers including breast cancer, suggesting that the consequent immune-suppressive environment contributes to cancer evasion." (PMID 31075939, 2019). "ER− breast cancer is associated with elevated NF-κB activity, and shows increased expression of certain cytokines (IL-6, IL-8) and chemokines (CCL5, MCP-1 [CCL2])." (PMID 30736340, 2019). "The circulating high levels of IL-6 in patients with breast cancer were shown to be positively associated with cancer metastasis and poor survival rate, consistent with the results of meta-analysis from a Kaplan–Meier Plotter." (PMID 31252615, 2019). "YAP/TAZ/IL-6/SRF were highly expressed in TNBC compared to luminal breast cancer subtypes and is associated with the enrichment of M CSCs." (PMID 31394796, 2019). "A marginal positive association was observed between the IL-6 level and breast cancer risk when IL-6 levels were categorised into two groups based on the 1.5-pg/mL cut-off value (crude OR = 1.38; 95% CI = 1.00, 1.90)." (PMID 30962499, 2019). "IL-6 increases the metastatic potential of cancer cells and its overexpression is linked with poor prognosis of breast cancer." (PMID 30155724, 2018). "Upstream of Jak2 and STAT3, IL6 is also linked to breast cancer metastasis: IL6 expression was found to be higher at the invasive leading edge of human primary breast cancer cells." (PMID 30558204, 2018). "Among these DEGs, IL6 was associated with several cancers, especially with leukemia, lymphoma, lungs, liver and breast cancers." (PMID 29593668, 2018). "Increased IL-6 has been reported in serum of breast cancer patients and associated with poorer prognosis." (PMID 29891854, 2018). "The interplay between Notch and IL-6 is even more complicated in breast cancer-associated bone metastasis." (PMID 30154786, 2018). "In patients with breast cancer, high levels of circulating IL-6 are associated with tumor progression, recurrence, and shorter survival time." (PMID 30546293, 2018). "The level of IL-6 has been shown to be directly correlated with breast cancer stage, which is indirectly associated with the prognosis of patients." (PMID 30111758, 2018).
breast cancer (continued). "IL-6 is a pro-inflammation cytokine and elevated levels are linked with poor prognosis of breast cancer." (PMID 30155724, 2018). "IL6 is associated with the progression of multiple cancers, including leukemia, lymphoma, breast cancer, kidney, and lungs cancer." (PMID 29593668, 2018). "It has been shown that a high plasma level of proinflammatory cytokine IL-6 is associated with the occurrence of cognitive impairment in postchemotherapy breast cancer patients." (PMID 29681766, 2018). "We examined the expression of EMT-associated proteins and genes in breast cancer cells after IL-6 signalling was blocked." (PMID 29891854, 2018). "Like IL-6, IL-8 is up-regulated in breast cancer tissues compared to normal breast cells and is associated with poor prognosis." (PMID 30155724, 2018). "IL6 was previously found to be secreted by ASCs, and it caused significant stimulation of MCF-7 breast cancer cell migration, while depletion of IL6 in the ASC conditioned media decreased migration and invasion." (PMID 29887999, 2018). "Specifically, the association between interleukin-6 (IL-6) and the pathogenesis of melanoma and breast cancer was studied." (PMID 28264501, 2017). "Circulating levels of IL-6 has been associated the progression of breast cancer and with advanced disease." (PMID 29387062, 2017). "Overall, our results align well with the known role of IL-6 in pro-metastatic processes and the emerging evidence for associations between rs1800795 polymorphisms and clinical outcomes in patients with breast cancer." (PMID 28732081, 2017). "Among premenopausal women, high TNF-α was associated with significantly increased breast cancer risk in the tertile model only (P trend = 0.017); and high IL-6 was associated with increased risk in the continuous model only (RR 1.58; 95% CI: 1.02–2.46)." (PMID 28983080, 2017). "We recently reported that interleukin-6 (IL-6), an inflammatory marker associated with breast pathology and the development of breast cancer, decreases with diet intervention and weight loss in both insulin-sensitive and insulin-resistant obese women." (PMID 28555011, 2017). "The IL6 rs1800795 SNP (-174G>C) is a focus of genetic studies on breast cancer risk because of its association with circulating IL-6 levels." (PMID 28555011, 2017). "MDA-MB-231 cells are known to express constitutively activated STAT3 pathway, principally through the engagement of an IL-6/IL-6R autocrine loop, and this pathway has been implicated in breast cancer oncogenesis." (PMID 28856117, 2017). "Elevated interleukin-6 (IL-6) has been consistently associated with breast pathology and the development of breast cancer." (PMID 28555011, 2017). "We found that plasma IL-6 was associated with increased breast cancer risk among premenopausal women, but only in the continuous model." (PMID 28983080, 2017). "Among these SNPs, rs1800795 (174 G>C) has emerged as especially important in affecting circulating IL-6 levels, and has been shown to be associated with extranodal extension as well as decreased disease-free and overall survival in breast cancer patients." (PMID 28732081, 2017). "Serum from one hundred and ten breast cancer patients and thirty healthy female volunteers, were prospectively collected and evaluated for serum levels of Shh and IL-6 using human Shh and IL-6 specific enzyme-linked immunoassays." (PMID 28496132, 2017). "IL-6 has also been implicated in the malignant transformation of breast cancer stem cells as well as in the enhancement of cancer cell metastatic potential and epithelial to mesenchymal transition." (PMID 28856117, 2017). "A small pilot study that included eight breast cancer patients who underwent chemotherapy during the study found associations of higher sTNFR2 and IL-6 levels with decreased gray matter volume in specific regions." (PMID 28616125, 2017).
breast cancer (continued). "We analyzed the association between IDO, IL-6 expression, plasma IL-6 level and clinicopathological features of breast cancer prior neoadjuvant chemotherapy." (PMID 29296206, 2017). "Our study indicates that higher concentrations of IL-6 and IL-8 were positively associated with increased risk of breast cancer, which is consistent with previous study." (PMID 29088874, 2017). "A recent meta-analysis (12 studies; 10,137 breast cancer cases, 15,566 controls) was unable to establish an association between IL6 genotypes and breast cancer risk." (PMID 28555011, 2017). "A crosstalk between LEDGF/p75 activation and the STAT3/IL6 inflammatory pathway, implicated in PCa, has also been identified in HaCaT skin cancer cells and in breast cancer cells." (PMID 28212536, 2017). "Interleukin 6 (IL-6) has emerged as an important factor in breast cancer progression with IL-6 single nucleotide polymorphism (SNP) variants shown to affect survival." (PMID 28732081, 2017). "IDO and IL-6 expression associated with advanced breast cancer and poor response to neoadjuvant chemotherapy." (PMID 29296206, 2017). "Data from patients with breast cancer suggest that IL-1β, IL-6, IL-8 and TNF-α contribute to chemotherapy-associated cognitive impairment." (PMID 28542626, 2017). "Several studies show that evaluated IL-6 is associated with many type of tumors such as breast carcinoma, colorectal cancer, lung cancer, ovarian cancer and lymphomas." (PMID 28548958, 2017). "For instance, adverse childhood experiences are associated with higher levels of circulating IL-6, which is known to be a tumor-promoting factor involved in breast cancer development and progression." (PMID 26910901, 2016). "Increased expression of IL-6 has been detected and associated with an unfavorable prognosis in patients with various types of cancers including breast cancer, colorectal carcinoma, and ovarian cancer." (PMID 27006530, 2016). "Elevated expression of IL-6 or its receptor are commonly found in many cancer types, including breast cancer, and are associated with poor prognosis." (PMID 27694691, 2016). "Secretion of IL-6 by cancer-associated fibroblasts has also been implicated in the suppression of ERα and tamoxifen resistance in luminal breast cancer cell lines." (PMID 26840088, 2016). "Correspondingly, a single STAT responsive element has been identified within the MUC1 promoter, that when mutated both decreases MUC1 promoter activity in breast cancer cells and also abolishes stimulation by interleukin-6 and interferon-gamma." (PMID 27768738, 2016). "Increasing evidence supports the notion that high levels of serum IL-6 are associated with poor prognosis, advanced disease, and metastases in breast cancer patients." (PMID 26840088, 2016). "Regarding IL-6, it is the most important cytokine associated with poor prognosis for breast cancer, and it is known for controlling breast cancer cell growth and regulating cancer stem cell renewal." (PMID 27282478, 2016). "Elevated circulating levels of IL-6 have been associated with reduced breast cancer survival and increased tumor burden." (PMID 26970739, 2016). "IL-6 induction in breast cancer cell lines reduces cellular adhesion which is associated with reduced e-cadherin expression." (PMID 28105072, 2016). "We now demonstrated that circulating IL-6 levels are associated with both chronological age and frailty in a selected breast cancer population." (PMID 25989735, 2015). "Association of inflammatory cytokines, resistin and IL-6 with breast cancer risk has been reported previously." (PMID 25868978, 2015). "IL-6 levels were associated with chronological age in both groups and with clinical frailty in older breast cancer patients, whereas telomere length, IGF-1 and MCP-1 only correlated with age." (PMID 25989735, 2015). "Expression of the pro-inflammatory cytokine interleukin-6 increases with pathological stage and grade, and is associated with poorer prognosis in breast cancer patients." (PMID 26268945, 2015).